EGFR (epidermal growth factor receptor)
Diseases named in the same sentence as EGFR in open-access papers (continued):
Sharing a sentence is not in itself a finding about the gene and the disease.
tumor (continued). "Xenograft studies confirm that monensin effectively inhibits tumor growth by suppressing cell proliferation through targeting EGFR signaling." (PMID 26639992, 2015). "Intensity of EGFR immunostainings, performed with the four different antibody clones varied both within one tumor sample as well as in different tumor specimens." (PMID 25227424, 2014). "The percentage of EGFR-positive tumours was significantly higher in the intestinal-type (80%) than in the diffuse-type (11.1%, p = 0.023)." (PMID 24454858, 2014). "Both classes of agents display significant anti-tumor activity in a range of EGFR-dependent mouse xenograft models." (PMID 25438047, 2014). "The staining intensity of the epidermal growth factor receptor (EGFR) produced a similar kinetic pattern, and the histological results were notably matched with the kinetics of clonogenic tumor cell repopulation." (PMID 24932228, 2014). "Mammary gland-specific human EGFR transgene expression under MMTV long terminal repeat induces neoplasia in mice." (PMID 25516216, 2014). "Several studies have demonstrated that EGFR expression is a strong prognostic indicator that correlates with both higher recurrence rates and shorter survival in different tumor entities." (PMID 25216514, 2014). "These authors observed synergistic treatment efficiency by a pronounced decrease in cell viability and tumour size upon simultaneous AurkA and EGFR targeting, revealing evidence for AurkA / EGFR signalling crosstalk." (PMID 24980817, 2014). "Isolated reports of intratumoral EGFR mutational heterogeneity often used less sensitive methods of detection or have been dismissed as MASI, i.e. heterogeneous distribution of mutant EGFR amplification within the tumor." (PMID 24742923, 2014). "Initial PET studies with fluorine-18-labeled reversible EGFR inhibitors in tumor-bearing animals demonstrated relatively low uptake or fast clearance of the reversible EGFRIs from the tumor area, at least in part due to active efflux from tumor cells." (PMID 25484865, 2014). "Collectively, these mechanisms clearly demonstrate the multitude of adaptive strategies developed by the tumor to ensure its continued growth and underscores the complexity of treating EGFR-TKI-resistance disease." (PMID 25101246, 2014). "As both gefitinib and erlotinib are now registered in Europe for the treatment of patients with an EGFR mut + tumour, selection criteria to identify which patients are most likely to have an EGFR mutation are needed." (PMID 25264519, 2014). "In other forms of cancer where anti-EGFR therapy is used, molecular profiling of the tumor has become essential for customized medical treatment decision." (PMID 24899223, 2014). "Western blots showed expression of Akt1, p-Akt1 (pT308, pS473), PTEN, and EGFR in the tumor tissue homogenates." (PMID 25389442, 2014). "We finally investigated the in vivo antitumor activity of combined PAFR and EGFR targeting in nude mice bearing CAOV-3 cells that were grown subcutaneously as tumor xenografts." (PMID 24886678, 2014). "Transient activation of the EGFR signaling pathway in normal and tumor cells upon exposure to arsenic has been reported in several studies." (PMID 24927258, 2014). "EGFR gene overdosage resulting from chromosome 7 polysomy was detected in the G108 sample both in initial tumour and subsequent passages of culture." (PMID 25788865, 2014). "EGFR inhibition induces tumor cells to the mesenchymal phenotype, which cell type show resistant to EGFR inhibitor, via cytokines such as IL-6 and TGF-β." (PMID 25240937, 2014). "In conclusion, our data correspond favorably with other publications investigating EGFR-mAB use and primary tumor location in mCRC." (PMID 24816724, 2014). "While the role of EGFR and cMet as important targets promoting tumor growth is well understood, little is known about relationship between EGFR and cMet signaling and cell density." (PMID 25272226, 2014).
tumor (continued). "In this respect, it has been shown that EGFR inhibition induces c-Met activation in tumor-initiating cells in an EGFR-driven GBM mouse model." (PMID 24709958, 2014). "It would be interesting testing the effect of therapy scheduling on the response of tumours to anti-EGFR antibodies such as cetuximab." (PMID 25278152, 2014). "In order to interrogate this information on the pathways that play a dominant role in each tumor line (such as EGFR, RAS, PI3K, etc.), we used 3 anti-cancer agents (erlotinib, sorafenib and dasatinib) targeting these pathways." (PMID 24884660, 2014). "EGFR expression evaluated with scoring method (A) showed for all of the four antibodies fewer numbers of EGFR positive tumor samples for all of the four antibodies in SCC and ADC than evaluated with method (B) and (C)." (PMID 25227424, 2014). "The overall balance of EGFR trafficking towards degradation or signalling very much affects the response of tumor cells to EGFR inhibitors." (PMID 25238453, 2014). "Adenocarcinoma is by far the most common NSCLC histology in South-East Asia, and about 40% of these tumours are EGFR mutant." (PMID 25264519, 2014). "Testing for the presence of specific cell-surface receptors (such as EGFR or HER2) on tumor cells is an integral part of cancer care in terms of treatment decisions and prognosis." (PMID 24337485, 2014). "Over many years the epidermal growth factor receptor (EGFR) has been investigated as a major target for the treatment of uncontrolled tumor growth." (PMID 24603603, 2014). "A combined parameter on tumor micromilieu, specifically perfusion, and EGFR expression, appeared as a candidate biomarker for tumor response—this parameter can be measured using PET imaging with 86Y-cetuximab as a tracer." (PMID 24603603, 2014). "EGFR is a signaling hub for an increasing list of growth factors, cytokines and inflammatory mediators that connects the inflammatory reaction to tumor development." (PMID 24722433, 2014). "When the expression of EGFR is decreased, inhibition of downstream signaling occurs in malignant tumor cells." (PMID 24723942, 2014). "18F-FLT PET has also been shown to be a more sensitive tool that can provide an early identification of tumor response for radiotherapy, chemotherapy or EGFR inhibitor drugs." (PMID 24932228, 2014). "We previously generated a diabody format of tumor-targeted TRAIL termed DbαEGFR-scTRAIL, comprising single-stranded TRAIL molecules (scTRAIL) and the variable domains of a humanized variant of the EGFR blocking antibody Cetuximab." (PMID 25198428, 2014). "One such tumor antigen that is overexpressed on tumor cells is the epidermal growth factor receptor (EGFR)." (PMID 24932299, 2014). "Overall, EGFR overexpression (percentage of immunoreactive tumor cells, ≥50%) was identified in 59.6% of the patients." (PMID 24944678, 2014). "We propose that the inhibition of EGFR at the levels of expression and activity should be used as a new strategy, as it exhibits far superior results for EGFR-dependent tumor inhibition." (PMID 24801752, 2014). "A patient cohort of 146 subjects with NSCLC was investigated and specific immunostaining for c-Kit as well as fluorescent in situ hybridization (FISH) for EGFR was performed using the tumor samples." (PMID 25013472, 2014). "Gefitinib exerted anti-tumor effect by inhibiting EGFR-driven signaling activation such as Akt and ERK1/2 in the sensitive NSCLC cells." (PMID 24884778, 2014). "It showed higher potency than erlotinib and lapatinib in most of the tumor lines tested, with an EGFR and HER2 in vitro kinase IC50 of 2.4 and 15.7 nM respectively." (PMID 25251190, 2014). "By comparison the EGFR PCR test required macrodissection only if the tumor content was <10% and can be performed in one day using a single 5 μm section." (PMID 24586842, 2014). "By contrast, significant correlations were identified between tumor size and EGFR expression and tumor size and PR expression." (PMID 25364399, 2014).
tumor (continued). "In an A431 xenograft tumor model, Hermiston and coworkers were able to show significant inhibition of tumor growth when the anti-EGFR antibody-expressing AAV1 was administered intramuscularly in both prophylactic and therapeutic settings." (PMID 24473340, 2014). "qPCR analysis of amplified DNA demonstrated reproducible detection of copy number changes of the EGFR in captured tumor cells." (PMID 24886394, 2014). "The first case has been described for the amplification of EGFR, which in some GBMs is found preferentially at the invading edge of the tumor, indicating a sort of “functional specialization” of a tumor subpopulation." (PMID 24473088, 2014). "The purpose of this study is to clarify and to validate in clinical testing conditions the accuracy of EGFR genotyping using different tumor sites and various types of samples (transthoracic, surgical or endoscopic biopsies and cytology specimens)." (PMID 24885034, 2014). "Five of the eight tumor cell lines had significantly (p<0.05) higher basal EGFR phosphorylation levels in the 3D spheroids than the 2D monolayer culture." (PMID 24638075, 2014). "It′s demonstrated that overexpression of miR-7 inhibited schwannoma cell growth both in culture and in xenograft tumor models in vivo, which correlated with downregulation of EGFR, Pak1 and Ack1." (PMID 24816687, 2014). "In the mutant K-ras-driven PDA model, EGFR controls the differentiation of neoplastic precursors and induces tumor initiation, following which, EGFR promotes cancer progression by activating ERK." (PMID 24932227, 2014). "At cut off value of ≥5%, tumour specimens from 43%, 77%, 52% and 92% of cases were EGFR, HER-2, HER-3 and HER-4 positive respectively." (PMID 24609222, 2014). "For example, High EGFR expression of tumor cells was shown to predict the benefit of anti-EGFR therapy such as cetuximab." (PMID 24886394, 2014). "The present experiments are the first to test the effect of combined fractionated irradiation and an EGFR/ErbB-TK inhibitor on tumour growth time and local tumour control." (PMID 25444177, 2014). "Cetuximab and panitumumab are monoclonal antibodies approved for the treatment of refractory CRC that block the epidermal growth factor receptor (EGFR) signaling pathway in tumor cells and, thus, can slow tumor progression." (PMID 24788807, 2014). "Second, the inhibition of both EGFR and Notch signalling pathway is dramatically more effective for suppressing tumor growth than blocking EGFR or Notch signalling pathway alone." (PMID 24864230, 2014). "Different ADC tumor samples show varying results in EGFR expression according to the different scoring systems (A), (B) and (C)." (PMID 25227424, 2014). "The evaluation of EGFR gene status by FISH is delicate: EGFR gene variations in tumor cells are focal and low levels of EGFR amplification are difficult to visualize." (PMID 25227424, 2014). "Given its important role in tumor growth and proliferation, the EGFR pathway has been the focus of intense clinical investigation across many tumor sites." (PMID 25221748, 2014). "Here we show that the prolyl hydroxylase PHD3 restrains tumour growth in response to microenvironmental cues through the control of EGFR." (PMID 25420773, 2014). "In support of this, neoadjuvant treatment of primary tumors with gefitinib or gefitinib plus anastrozole in a postmenopausal, EGFR+ cohort reduced proliferation, EGFR activation and tumor size." (PMID 25116921, 2014). "The concordance between EGFR status in tumour and plasma/serum samples varies from 58% to 93% in these studies." (PMID 24773774, 2014). "It is apparent that the persistent activation of PAFR in the face of EGFR blockade still contributes to tumor growth and resistance." (PMID 24886678, 2014).
tumor (continued). "IR also induces expression of the transforming growth factor β (TGF-β) and thereby TGF-β-mediated epithelial-to-mesenchymal transition in mammary epithelial cells, and activation of the epidermal growth factor receptor (EGFR) thereby promoting tumor growth." (PMID 25052686, 2014). "We also demonstrated the rare presence of EGFR-activating mutation in isolated CTC-DNA and cf-DNA, as well as original tumor-biopsy samples via targeted somatic mutation." (PMID 24999991, 2014). "Co-existence of p-EGFR signal and nuclear C/EBPβ signal can be found in a large fraction of the tumor cells which were analyzed, which implies the parallel presence of EGFR and C/EBPβ co-activation in these tumor cells." (PMID 25229239, 2014). "In a study that had 25 cases of cpAC, 80% of the tumors expressed EGFR and of the cpACs that had EGFR, the percentage of tumor cells counted as positive ranged from 20-100%." (PMID 24423144, 2014). "Normally, the EGFR/MAPK (mitogen-activated protein kinase) pathway is one of the major pathways driving tumor cell proliferation, whereas the activity of the PI3K pathway decreases due to the function of phosphatase and tensin homolog (PTEN)." (PMID 25505849, 2014). "The first modality was tumor growth factor α-Pseudomonas exotoxin 38 (TGFα-PE38), which specifically targets and kills tumor cells that express the epidermal growth factor receptor." (PMID 24932299, 2014). "Decorin's binding to EGFR initially leads to receptor's prolonged activation, followed by EGFR internalization and degradation, eliminating tumor growth and metastases." (PMID 25140302, 2014). "The possible mechanisms behind the positive effects of EGFR–TKI retreatment are as follows: (I) Tumor cell heterogeneity." (PMID 25610713, 2014). "The combination of EGFR with STAT3 inhibitors has shown improved anti-tumor activity in other pre-clinical models; certainly, data from the current study would support further investigation of combining Dacomitinib with a STAT3 inhibitor for SCCHN." (PMID 24853121, 2014). "Synthetic lethal screening of an EGFR-centered signaling network using a siRNA library revealed that STAT3 is one of the targets that synergize with EGFR antagonists to reduce cancer cell viability and tumor size." (PMID 24662938, 2014). "An exploratory object of the TRIGGER study was to evaluate the correlation between EGFR testing results obtained from basal tumor biopsies and circulating tumor cells." (PMID 25137181, 2014). "STAT3 has been proposed as a therapeutic target for tumor cells as it is a downstream mediator of EGFR and IL6, both of which have been shown to be important in carcinogenesis and angiogenesis." (PMID 24404126, 2014). "Antibody 2.1E1 was the most sensitive antibody: we obtained highest numbers of EGFR-positive tumor samples using this clone in immunostainings for all of the three scoring methods." (PMID 25227424, 2014). "Internalization of EGFR/ligand (EGF or anti-EGFR antibodies) complex is a physiological mechanism affecting the tumor cell response to growth and inhibition stimuli." (PMID 25238453, 2014). "In this study, we specifically investigated the mechanisms by which EGFR inhibition modulated anti-tumor responses." (PMID 25240937, 2014). "EGFR is the target of many chemotherapeutical approaches because EGFR activation results in cell signaling cascades that promote tumor growth." (PMID 25386651, 2014). "Small interfering RNA knockdown of SNX1 levels in tumor cell lines resulted in increased proliferation, decreased apoptosis, decreased anoikis, increased EGFR phosphorylation after EGF stimulation, and increased downstream signaling." (PMID 24700353, 2014). "Suggested mechanisms for its tumor-suppressive ability include 1 directly binding and downregulating EGFR 32, 2 interfering with angiogenesis 33, and 3 inhibiting cell migration and growth by suppressing β catenin levels." (PMID 24634138, 2014).
tumor (continued). "On the molecular basis, SRC regulates multiple signaling cascades associated with tumor development and progression, including the focal adhesion kinase (FAK) pathway, the epidermal growth factor receptor (EGFR) pathway, and the Ras/ERK pathway." (PMID 25140799, 2014). "We show that treatment with P7170 results in a marked reduction in the survival of NSCLC cells with different mutations in EGFR, KRAS, PIK3CA, or PTEN and inhibition of tumor growth in vivo." (PMID 25466244, 2014). "The epidermal-growth-factor receptor (EGFR) is part of a signalling pathway that regulates tumor cell proliferation, invasion, angiogenesis, metastasis, and apoptosis." (PMID 24836053, 2014). "Previously, we reported that the Drosophila SOCS-box protein, Socs36E, potentiates EGFR-driven tumor formation and metastasis." (PMID 25180228, 2014). "For instance, it is well established that in a subset of GBMs, the epidermal growth factor receptor mutant EGFRvIII is present only in a subpopulation of tumour cells, influencing surrounding cells by paracrine mechanisms." (PMID 24154962, 2014). "In vivo, Dacomitinib treatment delayed tumor growth, while decreasing phospho-EGFR and Ki-67 immunoexpression." (PMID 24853121, 2014). "In an EGFR mutant NSCLC patient's tumor biopsy, a subpopulation of mesenchymal tumor cells was identified, which subsequently appeared to give rise to resistance to EGFR inhibitor therapy." (PMID 25193862, 2014). "In the phase I study of AZD9291 in EGFR mutant patients resistant to standard EGFR TKIs, 50% of patients experienced tumor shrinkage and the drug worked particularly well in patients with the T790M mutation." (PMID 25364578, 2014). "The induction was only slight and the most likely reason for this is the presence of both high EGFR activity and high endogenous miR-31 expression in the tumor cells." (PMID 25229239, 2014). "Previous studies have reported significant associations between serum MUC1 and VEGF levels and tumor response, PFS and OS in patients with advanced NSCLC treated with EGFR-TKIs." (PMID 25410981, 2014). "Based on its central role in cellular tumor growth, EGFR is intended as favored drug target for the development of specific anti-NSCLC treatments." (PMID 25227424, 2014). "As part of a broad investigation, we analyzed EGFR expression in tumor samples of NSCLC patients by IHC using four different EGFR specific antibody clones and three scoring methods and correlated these data with FISH analysis." (PMID 25227424, 2014). "Immunohistochemical (IHC) staining of 38 tumor specimens from HNSCC patients showed that the expression of p-AMPK or EGFR was heterogeneous." (PMID 24457597, 2014). "A homogenous distribution was found for the EGFR concentration in the tumor patients and control groups." (PMID 25120668, 2014). "We analyzed paraffin sections from 10 GBM with EGFR amplification, retrieved from our CGHa database, using CD31 monoclonal antibody to identify endothelial cells and FISH detection of EGFR amplification to identify tumor cells." (PMID 24868550, 2014). "A high degree of concordance between mutation data in tumor tissue and CTC preparations was observed for EGFR exon 19 deletions." (PMID 25137181, 2014). "Other EGFR inhibitors have been combined with IR, all consistently supporting this combinatorial strategy for anti-tumor efficacy." (PMID 24853121, 2014). "One possibility is that the EGFR GCN high cells possess biological activities that determine the outcome of the entire tumor cell population." (PMID 24940619, 2014). "In this study, the role of EGFR in tumor angiogenesis was examined in H292 NSCLC cells under the pretense that confluent cells would exhibit a more angiogenic and growth-centered phenotype." (PMID 25272226, 2014). "In this tumor EGFR amplification was seen across all tumor regions, while amplification of both PDGFRA and KIT was detected in two of five regions." (PMID 25608559, 2014).